IL1A (interleukin 1 alpha)
Diseases named in the same sentence as IL1A in open-access papers (continued):
Sharing a sentence is not in itself a finding about the gene and the disease.
melanoma (continued). "Mechanistically, IL-1α and IL-1β secreted by melanoma cells increase COX-2, PD-L1, and PD-L2 expression levels in tumor associated fibroblasts which, in turn, suppress the function of tumor-infiltrating T cells." (PMID 32604720, 2020). "To date, previous studies have shown that EDPs and/or VGVAPG peptide increase the production and/or secretion inflammatory markers such as IL-1α, IL-1β, and IL-6 in ligamentum flavum cells, synovial cells, and melanoma cell lines." (PMID 32463311, 2020). "On the other hand, blocking secreted IL-1α in melanoma cells is sufficient to diminish NF-κB activation and amoeboid features." (PMID 30712866, 2019). "We propose that, after surgical removal of the primary melanoma lesion, the amoeboid phenotype should be targeted using either ROCKi or IL-1α blocking antibodies as therapies to restrict immunosuppressive microenvironments and metastatic dissemination." (PMID 30712866, 2019). "Studies have confirmed that IL-1β, IL-1α, IL-6, IL-8, IL-18 and their receptors are permanently expressed in malignant melanoma cells, suggesting that chronic inflammation exists during the melanoma development." (PMID 30149677, 2018). "In our investigation, the mRNA level of IL-1α, IL-1β, and IL-18 were all decreased, indicating the suppression of the inflammatory environment in human melanoma." (PMID 30149677, 2018). "First, we confirmed the presence of an inflammatory microenvironment in melanoma and detected increased IL1A and IL1B expression in stage-III and stage-IV melanoma patient samples." (PMID 28450382, 2017). "A role for host-derived IL-1β, and to a lesser extent IL-1α, in the neovascularization and metastasis of melanoma allografts has been established using recombinant mice." (PMID 28450382, 2017). "The abundance of ADAM9 RNA measured by RT-PCR is decreasedin vitro in human melanoma cells after culture with collagen type I or with Interleukin 1 alpha (IL1α) compared to mock stimulated conditions." (PMID 27990250, 2015). "In a different study on melanoma patients performed by the Grimm group, IL-1α was expressed in most primary tumors (98%) and approximately half (55%) of metastases." (PMID 23847618, 2013). "IL-1α pretreated mice had 11-22-fold greater hepatic melanoma tumor burden than control mice pretreated with saline presumably through altering adhesive interactions between B16F1 cells and the hepatic microvasculature." (PMID 16336680, 2005). "Liver sections from IL-1α-pretreated mice attracted 3-fold more melanoma cells to adhere in vitro than control liver sections." (PMID 16336680, 2005). "In addition, RSC-EXO reduced melanin production in α-MSH-stimulated B16F10 melanoma cells and suppressed the secretion of pro-inflammatory cytokines, including IL-1α, IL-6, and TNF-α, in LPS-stimulated RAW 264.7 macrophages." (PMID 42278464, 2026). "Earlier studies showed IL-1α, a cytokine that can orchestrate an inflammatory response in the tumor microenvironment, mediates the innate and acquired resistance to immunotherapy in melanoma cells." (PMID 40574005, 2025). "Additionally, interleukin-1-alpha (IL-1α) increases PD-L1 expression on melanoma cells, further aiding in immune evasion by preventing immune detection and activity." (PMID 40872475, 2025). "Autocrine secretion of IL‐1α in amoeboid melanoma cells plays a key role in enhancing the positive feedback crosstalk between rho‐associated protein kinase (ROCK)‐Myosin II and proinflammatory nuclear factor κB (NF‐κB), that supports tumor invasion activity and metastasis." (PMID 38775220, 2024).
melanoma (continued). "The Mitf− cells were shown to produce larger amounts of IL-1α and IL-1β, compared to Mitf+ cells; in addition, the supernatant of Mitf- melanoma cells reduced Mitf expression in positive cells via the signalling of IL-1R, which we previously found was significantly upregulated in the caerin group." (PMID 36497272, 2022). "For example, TAMs upregulate urokinase-type plasminogen activator (uPAR) and secrete MMPs, such as MMP-9, which enable the remodelling of the ECM and increase the invasiveness of melanoma, or they upregulate such factors in melanoma cells through the secretion of TNFα and IL-1α." (PMID 34830780, 2021). "Specifically, treatment of CAF isolated from melanoma patients with IL-1α/β strongly inhibited the proliferation and function of melanoma-specific cytotoxic T cells, which was attributed to an upregulation of cyclooxygenase-2 and increased surface expression of PD-L1 and PD-L2." (PMID 34576054, 2021). "In addition, it has been demonstrated that BRAFV600E melanoma cells show an enhanced expression of IL-1α and IL-1β, which promoted the immunosuppressive properties of cancer-associated fibroblasts (CAF)." (PMID 34576054, 2021). "For the majority of our experiments, we used the A375 human melanoma cell line, which produces the IL-1α precursor in sufficiently high quantities and has been widely used for the study of IL-1α34,38, and U2OS cells, which proved suitable for microscopy studies and PLA analysis." (PMID 32332775, 2020). "Furthermore, constitutively activated BRAF(V600E) in melanoma tumor cells has been shown to initiate and sustain IL-1α/β-dependent T-cell suppression in a murine model." (PMID 32604720, 2020). "Moreover, the expression of BRAFV600E induced transcription of IL-1α and IL-1β in melanocytes and melanoma cell lines, which increased the suppression of proliferation and function of specific cytotoxic T cells in melanomas." (PMID 31775797, 2019). "Additionally, decreasing mRNA levels of IL-1α, IL-1β, and IL-18 further proved the negative regulation of CP on the melanoma inflammatory environment." (PMID 30149677, 2018). "In melanoma, PD-L1 expression on CAFs seems to be dependent of IL-1α/β secreted by melanoma tumor cells and melanocytes and could participate to the suppression of melanoma-specific CD8+ T cells." (PMID 29545811, 2018). "Although the role of MCP-1 in NHM biology is not known, MCP-1 potentiates tumor necrosis factor-α (TNF-α) and IL-1α in the stroma, and may potentiate early tumor growth and tumor angiogenesis in malignant melanoma." (PMID 27314341, 2016). "IL-1α and IL-1β transcript levels have been evaluated in melanoma, non-small cell carcinoma, colon, and squamous cell cancer cell lines via real-time qRT-PCR, and several of these cell lines exhibit significantly increased levels of IL-1α or IL-1β." (PMID 26176534, 2015). "IL-1α, IL-6 and IL-8 could provoke proliferation of keratinocytes and melanoma cells, respectively; moreover, IL-1α also could induce keratinocytes migration." (PMID 19272168, 2009). "Additionally, the angiogenic effects of IL-1 observed in the wild-type model were restored when IL-1β KO mice received plug implants containing melanoma cells with IL-1α." (PMID 17096856, 2006). "This analysis revealed a more pronounced pro-inflammatory signature of NHKs (IL-1α, IL-1β, and IL-8) under the dynamic influence of melanoma cells compared to samples treated only with SPNs, indicating that bidirectional crosstalk amplifies the modification of the hosting tissue by melanoma cells." (PMID 40869222, 2025). "Further, analysis of clusters identified within the melanoma patient set comparing patient outcome suggests that suppression of IL-1α, IL-4, IL-5, and CCL22, with concomitant elevation of CXCL10, CCL4, and CCL17, may correlate with more aggressive development of brain metastasis." (PMID 36527157, 2022).
melanoma (continued). "However, different authors have consistently maintained that EDPs induced the production and/or secretion of IL-1α, IL-1β, and IL-6 in ligamentum flavum cells, synovial cells, and melanoma cell lines; therefore, we can assume that caspase-1 should be activated by EDPs in these cells." (PMID 31691186, 2020). "Furthermore, we noticed an increase in DUSP1 (Dual Specificity Phosphatase 1), STK3 (Serine/Threonine Kinase 3), ACTA2 (Actin, alpha 2, smooth muscle, aorta) and IL1A (Interleukin 1α) gene expression levels; however, the role of these genes in melanoma repopulation remains to be addressed." (PMID 31597943, 2019). "This screening has shown that concentrations of 15 biomarker proteins (IL-1α, IL-1β, IL-6, IL-8, IL-12p40, IL-13, G-CSF, MCP-1, MIP-1α, MIP-1β, IFN-α, TNF-α, EGF, VEGF, and TNF-RII) were significantly higher in patients with resected high-risk melanoma compared with healthy controls." (PMID 28050120, 2016). "The roles of IL-1A and IL-1B have been extensively studied in various cancers, including non-small-cell lung cancer (NSCLC), head and neck squamous cell carcinoma, melanoma, colorectal adenocarcinoma, glioma, and cervical cancer." (PMID 41465261, 2025). "The secretion of TNF-α and IL-1α by activated TAMs triggers the production of IL-8 and VEGF-A by melanoma cells, resulting in enhanced angiogenesis and leakier vasculature." (PMID 38533720, 2024). "Recent studies have revealed that IL7 plays a significant role in glioma, melanoma and leukemia by contributing to anti-tumor effects through the release of cytokines, including IFNG, IL1A, IL1B, TNF, IL2 and IL4." (PMID 37958451, 2023). "In terms of plasticity, IL-1α and β can downregulate the expression of MITF and melanocytic antigens, favoring melanoma dedifferentiation and phenotype switching." (PMID 34604096, 2021). "In particular, IL1A mainly stimulates the expression of proinflammatory cytokines, including IL6 and IL8 in colon cancer and melanoma." (PMID 34203721, 2021). "Inhibition of BRAF/MEK signaling by silencer (si)RNA and pharmacological inhibition decreased the production of pro-tumorigenic factors such as IL-1α/β, IL-6, IL-8, IL-10, and VEGF by melanoma cells." (PMID 34576054, 2021). "Apte and his colleagues injected melanoma cells into C57BL/6 wild-type, Il1a, and Il1b knockout mice, respectively." (PMID 28360909, 2017). "Experiments with human malignant melanoma tissues and cell lines have shown that proinflammatory cytokines, such as IL-1α/β and TNF-α, produced by melanoma cells activate p38 kinase to promote the IFN-α/β-independent pathway of IFNAR1 degradation." (PMID 24516470, 2014). "Serum cytokine levels (including IL-1α, IL-1β, IL-2, IL-6, IL-10, IL-12, TNF-α, IFN-γ and IFN-α) were lower in A375 melanoma bearing mice treated with G3139 + VRP + ACV + PAC.PBP + DNR + X rays than in controls treated with physiological saline." (PMID 22233801, 2012). "A study of individual CSF samples from 22 patients with melanoma brain metastases and 5 disease-free controls found that Chemokine CCL22 and cytokines IL-1α, IL-4, and IL-5 were reduced in most samples, whereas a subset of molecules including CXCL10, CCL4, CCL17, and IL8 increased expression." (PMID 36527157, 2022). "Furthermore, in melanoma, I-BET151 also inhibits the production of cytokines and chemokines, such as IL-1α, VEGFC, IL-6, and IL-8." (PMID 34540687, 2021). "NLRP3 showed no changes in gene expression between control-RPE or AMD-RPE cells, while absent in melanoma 2 (AIM2) was 2.18-fold higher expressed in AMD-RPE cells when compared to control-RPE cells exposed to IL-1α priming and vehicle." (PMID 34202702, 2021). "The cisplatin-induced senescent melanoma cells activate the ERK1/2-RSK1 pathway through SASP components (such as IL-8 and IL-1α) to promote the growth of non-senescent melanoma cells." (PMID 34458273, 2021).
melanoma (continued). "In a study on melanoma cells, the inflammatory cytokines interleukin 1α (IL-1α) and TNFα, secreted by melanoma cells, but no other cytokines, were reported to stimulate the phosphorylation, and subsequent ubiquitination and degradation of IFNAR1." (PMID 32604862, 2020). "In line with this, IL-1α/β KO mice failed to develop solid tumor following injection of melanoma cells and exhibited improved survival compared to wild type animals, which died due to lung metastasis." (PMID 32825489, 2020). "Microglia-derived IL-1α and TNF-α were found to upregulate GM-CSF secretion from melanoma cells." (PMID 32668704, 2020). "IL-1α, IL-10, TGF-β, IL-8, and IL-4 mRNA were all upregulated during melanoma progression with a significant increase in metastatic compared to primary human melanomas suggesting transcriptional regulation." (PMID 30712866, 2019). "Although these findings do not provide a clear role for IL-1 in isolated melanoma cells in vitro, immunohistochemistry studies imply that IL-1α is uniformly expressed in naevi, primary tumors, and metastases and, thus, is unrelated to disease progression." (PMID 28450382, 2017). "Thus, we studied the pro-inflammatory pathway activity by measuring the expression of TNF-α inducible genes IL1-α, IL1-β, IL6 and IL8 across melanoma cell lines pairs." (PMID 27175588, 2016). "Human epidermal melanocytes (HEM) and MM96L melanoma cells were exposed to UVB radiation and IL-1α." (PMID 21961050, 2011). "They demonstrated that IL-1α/IL-1β knockout mice failed to develop solid tumors following injection of melanoma cells and exhibited significantly improved survival compared to the wild-type animals, which died due to lung metastases." (PMID 17096856, 2006). "Interleukin-1-α (IL-1α) and interleukin-1-β (IL-1β) upregulate MC1R mRNA in normal human melanocytes, while TNF-α and TGF-β, that potently repress melanogenesis in melanoma cells, moderately downregulate MC1R expression in normal melanocytes and mouse melanoma cells." (PMID 34356109, 2021). "Fibroblasts isolated from melanoma patient biopsies could directly suppress CD8+ T cells proliferation and function, via upregulating their expression of the PD-1 ligand PD-L1, mediated by IL-1α/β." (PMID 31428105, 2019). "The mechanisms of preferential IL-1α expression in human melanomas are not known." (PMID 23847618, 2013). "The immunosuppressive plasmacytoid DCs (pDCs) in human lung cancer TME secrete mature IL-1α due to the activation of absent in melanoma-2 (AIM-2)-like receptor (ALR)-based inflammasomes, which increase intracellular Ca2+, activating cytosolic calpains to generate mature IL-1α." (PMID 41294867, 2025).
viral infection (57 papers, 2011 to 2025). "IL-1A encodes interleukin-1 alpha, a pro-inflammatory cytokine that stimulates immune responses to viral infection and contributes to inflammation and immune regulation." (PMID 40927453, 2025). "The IL1A gene, encoding a member of the interleukin 1 cytokine family, is a pleiotropic cytokine involving in various virus infections, immune responses and inflammatory processes." (PMID 31114763, 2019). "Future studies investigating the association between the levels of IL‐1α and viral infection in the development of BOS would be of great interest." (PMID 26714197, 2016). "We, and others, have previously shown that peripheral viral infection is associated with glial activation, and increased expression of genes such as Tnf, Il1a and C1qa by microglia in response to peripheral inflammation has been shown to affect other glial subsets." (PMID 37596606, 2023). "Moreover, it has also been seen that IL-1α, a player of inflammatory response and IL-6, an interleukin involved in immune responses, inflammation and hematopoiesis, have been associated with viral infections such as SARS-CoV-2 and influenza virus." (PMID 39772252, 2024). "However, IL-1α could also be beneficial for the host immune reaction against viral infection, because IL-1R-deficient mice demonstrated an impaired immune response to vaccinia virus infection." (PMID 30787914, 2019). "IL-1A is an early-response pro-inflammatory cytokine that is rapidly up-regulated during many acute viral infections, including influenza A and dengue virus, where it amplifies local inflammation and recruits neutrophils and monocytes to sites of infection." (PMID 40927453, 2025). "Together, these data highlight that IL-1α induces changes in the gut microbiota uncoupled from viral infection." (PMID 38382577, 2024). "IL-1α represents a pro-inflammatory acute phase cytokine which is produced by macrophages and microglia and released following viral infection and CNS injury." (PMID 29666403, 2018). "Together these data demonstrate an essential role for IL-1α in mediating paracrine proinflammatory signaling following viral infection of primary differentiated epithelium." (PMID 27583193, 2016). "After pdmH1N1 virus infection, cigarette smoke exposed mice had significantly higher production of IL-1α, IL-1β, IL-2, IFN-γ, KC, RANTES on day 3; IL-5, IL-10 and MIP-1α both on day 1 and day 3 in the lungs than the control mice." (PMID 24465940, 2014). "Cytokines and chemokines that showed limited response in mice with any viral infection included Eotaxin, GM-CSF, IL-1α, M-CSF, IL-2, IL-3, IL-4, IL-5, IL-7, IL-9, IL-12p40, IL-13, IL-15, IL-17, MIP2, LIX, MIP1β, RANTES, IL-12p70, and VEGF (data not shown)." (PMID 23441208, 2013). "After viral infection, the amount of IL1α, IL-1β and IL-18 present in the cell medium was measured by ELISA." (PMID 23723976, 2013). "IL-1A and IL-1B are important inflammatory cytokines that mediate the inflammation and initiate the immune response against virus infection." (PMID 23927441, 2013). "Accumulating evidence has suggested that IL-1A and IL-1B play important roles in innate immunity against viral infection." (PMID 23927441, 2013). "Corneal cells are reported to produce a variety of cytokines during response to viral infection including IL-1α, IL-6, CXCL8, and low levels of IFN-γ." (PMID 22518343, 2012). "To test this, we injected animals daily with the anti-IL-1α or isotype antibodies during the course of cigarette smoke-exposure and viral infection." (PMID 22163019, 2011). "Viral infections have also been shown to stimulate the release of IL-1α from epithelial cells." (PMID 39127259, 2024). "In fact, numerous studies on different viral infections have shown IL-1α and IL-1β to induce NSCs to favor the astrocytic lineage rather than the neuronal lineage both in vitro and in vivo either via downstream induction of the transcription factor and, at the same time, impacting on neurogenesis." (PMID 39876841, 2024).